TLR4 (toll like receptor 4)
Diseases named in the same sentence as TLR4 in open-access papers (continued):
Sharing a sentence is not in itself a finding about the gene and the disease.
cancer (continued). "Recruitment of CD11c+ dendritic cells has been shown to occur upon the release of damage-associated molecular patterns (DAMPs) by dying cancer cells, and can trigger antigen uptake, maturation and presentation, via recognition by the TLR4 and activation of the type I interferon pathway." (PMID 25560237, 2015). "Thus, MFE is implicated in the defense against cancer by enhancing immune system function through TLR4 signaling-mediated activation of cytokines and immune cells." (PMID 26473845, 2015). "Our study and Cammarota found that stromal TLR4 expression is associated with cancer outcomes." (PMID 24887394, 2014). "Constitutive expression of some TLR4 genetic variants has also been linked to cancer." (PMID 25120541, 2014). "TLR4 is associated with the important cancer-related outcomes of survival and stage." (PMID 24887394, 2014). "However, the function of TLR4 at the protein level will be impaired by SNPs in TLR4 gene, subsequently leading to an altered susceptibility to chronic inflammatory diseases and cancers." (PMID 25290654, 2014). "All these findings suggested that polymorphisms of TLR2 and TLR4 might contribute to risk of human cancer." (PMID 24376595, 2013). "However, the association between TLR4 rs4986791 and cancer risk was significant in both South Asians and East Asians, but not in Caucasians." (PMID 24376595, 2013). "The identification of TLR4 Asp299Gly and Thr399Ile mutations might be important for the individual risk assessment of cancer patients treated by chemotherapy." (PMID 24250621, 2013). "Finally, we revealed that high expression of TLR4 in HCC tissues was strongly associated with both poor cancer-free survival and overall survival." (PMID 22938142, 2012). "We examined the function of TLR4 in telomerase deficient mTERC−/− mice harbouring chromosome instability which did not develop any overt immunological disorder in pathogen-free condition or any form of cancers at this stage." (PMID 20686699, 2010). "Moreover, TLR4 is implicated in immune activation across various cancers." (PMID 38930793, 2024). "In conclusion, the downstream pathways activated by TLR2 and TLR4 include positive feedback loops, and TLR4 expression levels are associated with more severe disease states in inflammatory responses, such as neuroinflammation, cardiovascular disease, and cancer." (PMID 36674552, 2023). "This may reflect a situation in which mouthwashes containing alcohol or other anti-bactericidal agents remove both pathogenic and beneficial oral bacteria, upsetting the balance of TLR6 and TLR4 signaling and potentially increasing the risk of cancer development." (PMID 37232814, 2023). "Therefore, it is suggested that TLR4 rs1927914 may be associated with the occurrence of certain cancer type." (PMID 33585082, 2021). "Notably, COX-2 is implicated in TLR4 and NF-κB signaling in inflammatory diseases and cancer." (PMID 34509494, 2021). "Therefore, Zhang and colleagues tested the hypothesis that endogenous TLR4 agonists induce the muscle wasting associated with cancer cachexia." (PMID 31480237, 2019). "Likewise, TLR4 has been known as indicative molecule for the detection of predisposition to cancer." (PMID 29883450, 2018). "Therefore, it is hypothesized that the expression level of TLR4 is associated with PD-L1 in cancer cells." (PMID 28484456, 2017). "The findings suggested that TLR4 polymorphisms may serve as a genetic risk factor for cancers." (PMID 29246004, 2017). "TLR4 expressed in normal and low-grade tumors could therefore be a contributing factor in chronic inflammation that promotes carcinogenesis, while decreased TLR4 expression in more aggressive high-grade tumors could result from loss of cell differentiation that accompanies cancer progression." (PMID 22110526, 2011). "Growing evidence suggests that mutation of TLR4 gene may play a role in the development of cancers." (PMID 21559380, 2011).
cancer (continued). "A growing body of evidence shows that TLR4 activation in cancer, immune and stromal cells upregulate gelatinase expression and activity, linking innate immune responses to extracellular matrix (ECM) remodelling." (PMID 42121921, 2026). "AMK polysaccharide • Enhanced phagocytosis by BMDMs• Activated expression and secretion of immunomodulatory factors (IL-6, IFN-λ, TNF-α, and NO) in BMDMs through TLR4 and MyD88The TLR4/MyD88 pathway plays a vital role in anti-cancer effects of AMK." (PMID 40144663, 2025). "While the current study focused on its anti-inflammatory effects, it is worth noting that compounds targeting TLR4/MD2 signaling have shown promise in modulating immune responses in cancer." (PMID 39976020, 2025). "Our findings, together with emerging evidence from other cancer types, establish the LPS/TLR4/NF-κB axis as a conserved pathway that shapes the immunosuppressive landscape across diverse tumors." (PMID 41235258, 2025). "eHsp90 interacts with cell-surface receptors, including low-density lipoprotein receptor-related protein-1 (LRP1) and toll-like receptors (TLR2 and TLR4), thereby promoting cancer cell proliferation, migration, and invasion." (PMID 41226319, 2025). "Remarkably, TLR4 and AGER share a common ligand, the high-mobility group box 1 (HMGB1), a damage-associated molecule extensively implicated in cancer pathogenesis." (PMID 40647480, 2025). "This research advances our understanding of NPF pathways in cancer and highlights TLR4 as a promising target for therapeutic intervention." (PMID 40696496, 2025). "It activated the intracellular signal transduction mechanism related to NF-κB and the cell surface receptor TLR4, and further upregulated the downstream pro-inflammatory factors, culminating in the aggravation of cancer inflammation." (PMID 40839565, 2025). "Increased expression of TLR-4/9 mRNA/protein expression in cancer tissue, presence of periodontal pathogens [F.n., P.g., T.d.] in mouth smear samples, and gingival inflammation/recession were associated with OSCC incidence." (PMID 40924302, 2025). "tiRNA-Gly-GCC-1 binds to its target, TLR4, and acts as a ‘sponge’, activating the immune escape of cancer cells and promoting the proliferation and metastasis of UBC." (PMID 40265011, 2025). "On the other hand, activation of TLR4 can enhance an immune response (e.g. T lymphocytes) that will result to inhibition of cancer cell proliferation." (PMID 40871563, 2025). "Previous studies have implicated lipopolysaccharide (LPS)-induced Toll-Like Receptor 4 (TLR4) activation in promoting proliferation and metastasis in various cancers." (PMID 39941749, 2025). "Propolis and its phenolic substance CAPE can inhibit the proliferation of cancer MDA-MB-231 cells in the inflammatory microenvironment by suppressing the TLR4 signaling pathway." (PMID 40944219, 2025). "The mechanistic pathway linking F. nucleatum to cancer involves adhesion to epithelial cells, followed by internalization and activation of TLR4/MYD88 signaling." (PMID 40869140, 2025). "On the other hand, recent data also suggest that signaling along endotoxin-TLR4 axis contributes to progression of several cancer types." (PMID 40868123, 2025). "Computationally validated to have strong TLR4 interactions, these vaccines show promise for early cancer vaccination." (PMID 41293317, 2025). "The Toll-like receptor (TLR) family, particularly TLR4, has emerged as a key player in linking inflammation to cancer development." (PMID 40703545, 2025).
cancer (continued). "Specifically, it has been demonstrated that HMGB1 release from dying cancer cells enhances antigen processing and presentation on dendritic cells (DCs) through the TLR4-MyD88 axis, a process that occurs during chemotherapy or radiotherapy." (PMID 41153383, 2025). "In hepatocarcinogenesis, disrupted gut microbiota and translocated lipopolysaccharides (LPS) promote cancer development through the Toll-like receptor (TLR4)-dependent pathways." (PMID 39931363, 2025). "Increasing evidence indicates that TLR4 expression plays a pivotal role in cancer progression and treatment resistance." (PMID 41332426, 2025). "Our results are consistent with prior studies linking TLR4 activation to enhanced migratory and invasive behaviors in various cancer types." (PMID 41332426, 2025). "TLR4 is involved in a broad spectrum of biological processes beyond innate immunity, including pain, addiction, reproduction, and cancer." (PMID 40959069, 2025). "Research has demonstrated that Fusobacterium nucleatum can enhance cancer growth and metastasis by releasing toll-like receptor 4 (TLR4), which interacts with BC cells via extracellular vesicles." (PMID 40161368, 2025). "TLR4 signals through the adaptor protein MyD88 and contributes to insulin resistance as well as cancer cell invasion and metastasis." (PMID 40647480, 2025). "We subcutaneously implanted WT and Cdk2-/- cancer cells into C57 mice and Tlr4-/- mice respectively." (PMID 40557162, 2025). "Activation of either or both TLR2 and TLR4, and further downstream signaling via the MyD88 and NFκB pathway, has been shown in other cancerous tumors as well as mycotic keratitis." (PMID 40725140, 2025). "NF-κB is well understood to be involved in many molecular processes, such as IL-6, TNF-α, and TLR4, in cancer." (PMID 38997762, 2024). "This review provides a comprehensive review of the role of the TLR4 signaling pathway in CRC, covering its significance in inflammation and cancer, as well as the potential applications of traditional Chinese medicine in regulating the TLR4 signaling pathway." (PMID 38930793, 2024). "TLR4 activation in cancer cells can promote the upregulation of anti-apoptotic proteins and DNA repair mechanisms." (PMID 38792335, 2024). "TLR4 plays a crucial role in innate immunity and the activation of adaptive immune responses in several diseases, including cancer." (PMID 39684439, 2024). "The use of natural and synthetic TLR4 agonists in vaccine formulations has been extensively tested in cancer and infectious disease vaccines." (PMID 39037263, 2024). "TLR4 acts as a master regulator in CRC growth under a high-fat diet by orchestrating cancer metabolism." (PMID 38930793, 2024). "Asparagus polysaccharide, one of its constituents, demonstrates cancer therapeutic potential by inducing apoptosis in MDSCs via the TLR4/NF-κB pathway." (PMID 38930793, 2024). "Arctiumlappa root (Niubang) activates TLR4 signaling, enhancing apoptosis, and reducing cancer cell attachment." (PMID 38930793, 2024). "For instance, neutrophil elastase (NE), which is released from the neutrophil extracellular traps (NETs) activated toll-like receptor 4 (TLR4) on cancer cells, has been shown to trigger the TLR4/p38/PGC1α axis, resulting in PGC1α upregulation." (PMID 38774408, 2024). "HMGB1 activates inflammatory cytokines through TLR4, contributing to cancer, by enhancing expression via NF-κB and STAT3 signaling pathways." (PMID 38930793, 2024). "The complexity of these interactions is highlighted by recent studies revealing the role of Toll-like receptor 4 (TLR4) in creating premetastatic niches for metastatic cancer stem cells." (PMID 39244591, 2024). "This prompt upregulation and consecutive decrease in TLR4 +IR cells is related to an immediate immune response and late neural damage due to cancer-induced neuropathy." (PMID 38730655, 2024).
cancer (continued). "Previous studies have shown that CIRT-damaged cancer cells participate in anti-cancer immunity by activating HMGB1/Toll-like receptor 4-mediated inflammatory responses." (PMID 38474078, 2024). "AcF2 also inhibited cancer cell growth, but showed a tendency of reduced activity with Tlr4−/− macrophages." (PMID 38396285, 2024). "Zhang found that gastric cancer Ti-EVs induced neutrophil autophagy and tumor precursor activation through the HMGB1/TLR4/NF-κB signaling pathway, promoting cancer cell proliferation and migration." (PMID 38598014, 2024). "Previous studies on CIRP as a modulator of inflammation in cancer have revealed that CIRP can act as a damage-associated molecular pattern (DAMP) and stimulate MyD88-NFκB and its subsequent cytokine release via Toll-like receptor 4 (TLR4) binding." (PMID 38397942, 2024). "TLR4 is a transmembrane protein with an approximate mass of 95 kDa, identified as overexpressed in different types of cancer, playing key roles in the development and progression of this disease." (PMID 39640496, 2024). "Knocking down TLR4 changes the metabolic enzyme profile, eliminating high-fat diet-enhanced ATP production and cancer growth." (PMID 38930793, 2024). "It exhibits potent cytotoxicity against cancer cells, modulating TLR4 signaling molecules and suggesting immunomodulatory potential." (PMID 38930793, 2024). "L7/L12 Ribosomal-protein, often referred to as TLR4 binder, was used as it has been shown in prior studies to generate a robust immune response when employed as an adjuvant in disorders like cancer, etc." (PMID 39050853, 2024). "In this context, we showed that Dectin-1, TLR2, and TLR4 are important for the basic activity of MDSCs in a fungal disease, bringing to light discoveries recently evaluated in the context of cancer and other diseases." (PMID 39035356, 2024). "In vitro study has demonstrated that PAI-1 on cancer cells binds TLR4 and promotes TGF-β secretion in macrophages by increasing IL-6 production via NF-κB activation." (PMID 38397187, 2024). "Studies indicate that TLR4 signaling can promote cancer cell proliferation, invasion, and resistance to apoptosis." (PMID 39273213, 2024). "The Toll-like receptor 4 (TLR4) gene is associated with innate immunity and has recently been associated with several cancer types." (PMID 38606218, 2024). "The TLR4/NF-κB inflammatory signaling pathway is involved in inducing the expression of multiple inflammatory cytokines in cancer." (PMID 38313314, 2024). "TLR4, a member of the pattern recognition receptor TLRs family, plays a crucial role in cancer development by regulating the production of chemokines and pro-inflammatory cytokines." (PMID 38833016, 2024). "Through activation of the TLR4/MyD88-dependent cascade, they elicit macrophage stimulation, initiating an immune response against cancer." (PMID 38930793, 2024). "MMP9, a member of the MMP family, contributes to infiltration invasion by breaking down the extracellular matrix, ultimately enhancing cancer growth and dissemination in the context of TLR4 signaling." (PMID 38930793, 2024). "Activation of the TLR4/NF-κB pathway promotes cancer cell survival and also increases the expression of anti-apoptosis proteins, such as Bcl-2, which results in reduced efficacy of chemotherapy." (PMID 39451226, 2024). "They further engineered the cryo-silicified cancer cells to adsorb adjuvants such as ligands for Toll-like receptor 4 (TLR4) and TLR9." (PMID 39301248, 2024). "Safe and immunogenic MPL-adjuvanted vaccines are TLR4 agonists and have also been applied in cancer vaccines." (PMID 38399416, 2024). "In particular, TLR2 and TLR4 are known to orchestrate the so-called hepatic inflammation–fibrosis–carcinoma sequence (IFC), which frequently leads to HCC onset." (PMID 38473265, 2024). "In AOM/DSS-induced mice, Toll-like receptor 4 (TLR4) mediated intracellular nuclear factor-κB (NF-κB)-containing signaling cascades, encouraging the progression of cancer." (PMID 37200915, 2023).
cancer (continued). "Actually, despite the specific function of TLR4 in different cancers investigated by many studies, there are contradictions existing among those researches." (PMID 37553698, 2023). "TLR4 signaling and hypoxia are shown to contribute to the regulation of EMT in HCC cells, with TLR4+ cells exhibiting a more mesenchymal- and cancer stem cell (CSC)-like phenotype that is associated with more aggressive disease." (PMID 37345131, 2023). "Our study focused on understanding how TLR4 can enhance the effectiveness of immunotherapy, a treatment approach that harnesses the body’s immune system to fight cancer cells." (PMID 37345131, 2023). "TLR4 and pSTAT3 are key players in cancer inflammation and immune evasion; in MBC TLR4-pos CTCs correlated with a high risk of disease progression." (PMID 37046848, 2023). "In melanoma, neutrophils recruited by TLR4 signaling can induce cancer cells to migrate to endothelial cells, promoting cancer metastasis." (PMID 37691931, 2023). "On the other hand, TLR4 plays a key role in connecting inflammation and cancer invasion and progression." (PMID 36647071, 2023). "TLR4 signaling can improve HCC cancer vaccines, regulate the immune landscape of the HCC microenvironment, and impact various immune cells, including T cells, B cells, dendritic cells, neutrophils, myeloid-derived suppressor cells, and macrophages." (PMID 37896221, 2023). "Additional recent evidence suggests that palmitic acid-mediated TLR4-dependent pro-inflammatory signaling is specifically relevant in the context of cancer progression." (PMID 36830818, 2023). "Toll like receptor-4 (TLR4) has been reported to play an important role in maintain the stemness of cancer stem cells." (PMID 36647071, 2023). "TLR4 is an attractive target for controlling cancer development and optimizing treatment response due to its potent regulation of systemic immune responses." (PMID 35841426, 2023). "In cancer-induced skeletal muscle atrophy, overexpression of Toll-like receptor 4 (TLR4) leads to the phosphorylation of P300 by p38β MAPK, a central regulator of skeletal muscle atrophy." (PMID 38148899, 2023). "One of the mechanisms by which PPARs act to control cancer progression is to affect the NF-κB signaling pathway, or its upstream pathways, such as the Toll-like receptor 4 (TLR4) signaling pathway." (PMID 37109526, 2023). "And new evidence suggests that TLR4 can be expressed not only on immune cells such as macrophages and dendritic cells, but also on cancer cells." (PMID 37553698, 2023). "Resistin-mediated transduction pathways have been described in various cancer cells, including signaling through toll-like receptor 4 (TLR4) and activation of the PI3K/Akt/NFκB pathway." (PMID 38137922, 2023). "An in vitro study concluded that green tea catechins and omega-3 fatty acids such as EPA and DHA downregulate toll-like receptor 4 signaling, induced in cancers to facilitate cachexia." (PMID 37571328, 2023). "TLR4 activation on cancer cells can induce cell death through multiple mechanisms, including apoptosis and necroptosis." (PMID 37896221, 2023). "Mara Brancaccio (University of Torino, Italy) recently discovered that Morgana is released from cancer cells and in association with extracellular Hsp90 induces cancer cell migration via Toll-like receptors TLR2, TLR4 and LRP1." (PMID 36602710, 2023). "The interaction of HA and membrane receptor CD44 or Toll-like receptor 4 (TLR-4) sustains proliferation of cancer and the formation of fibrosis." (PMID 36906534, 2023). "Nevertheless, there have been inconsistences in impact of TLR4 activation on cancer cells across various cancer models." (PMID 37990304, 2023). "Regarding different functions of TLR4 receptors on the surface of immune or cancer cells, to further examine the effect of TLR4 activation in vivo, we selected LPS, a known stimulator for TLR4, to treat mice inoculated with LLC cells." (PMID 37553698, 2023).